ENSG00000307864 (novel transcript)
Synonyms: LINC03091
Gene: Long non-coding RNA gene on chromosome 4 (4,560,518 to 4,582,954, reverse strand). Ensembl gene ENSG00000307864.
Diseases named in the same sentence as ENSG00000307864 in open-access papers:
ENSG00000307864 is named in the same sentence as 1 disease in open-access papers, as found by Europe PMC text mining. Sharing a sentence is not in itself a finding about the gene and the disease.
ENSG00000307864 shares sentences with these, for which no sentence is quoted: bipolar disorder (1 paper).